GRB2 (growth factor receptor bound protein 2)
Diseases named in the same sentence as GRB2 in open-access papers (continued):
Sharing a sentence is not in itself a finding about the gene and the disease.
tumor (continued). "Research in BC showed that GRB2 is a pivotal molecule in tumor growth and downregulation of its expression can lead to inhibition of breast cells with high EGFR and ERBB2 expression levels." (PMID 34679042, 2021). "Results from these experiments demonstrated that miR-27b-3p mimics are able to inhibit GC cell viability and colony formation, while Grb2 ov counteracts miR-27b-3p-induced tumor suppressive effects on GC cells." (PMID 34162761, 2021). "GRB2 promotes tumor cell proliferation and inhibits apoptosis by activating the Ras/Erk pathway, while inhibiting the GRB2/Ras/Erk pathway can limit tumor development by promoting apoptosis." (PMID 34162761, 2021). "Abnormal expression of GRB2 promotes tumor malignancies by activating both PI3K/AKT and ERK/MAPK pathways." (PMID 34345012, 2021). "PAX4/ miR-27b-3p/Grb2 regulatory loop plays a significant role in GC tumor progression, which indicates that potential therapy biomarkers need to be further investigated." (PMID 34162761, 2021). "And study also demonstrated that growth factor receptor-bound protein 2 (GRB2) is the target of miR-433-3p that mediated the tumor inhibitory function of miR-433-3p." (PMID 33593390, 2021). "These functions make GRB2 a potential target biomarker to hinder tumor metastasis and local invasion." (PMID 33679866, 2020). "There were a lot of downstream signaling pathways, such as AKT and ERK, that were regulated by Grb2 and facilitated tumor progression." (PMID 30479571, 2018). "The cliques involving AKT1 (METH), PTEN (mRNA) and AKT1 (METH), PIK3R2 (mRNA) can be construed as tumor suppressing, while cliques involving AKT1 (METH), CCND1 (mRNA) and AKT1 (METH), GRB2 (CN) probably are tumor activating." (PMID 30059495, 2018). "For this analysis, we compared the Grb2 levels in the HCC specimens with those in the adjacent non‐tumour data sets and found that Grb2 was more highly expressed in the HCC tissue than in the non‐tumour specimens." (PMID 29575431, 2018). "AKT and ERK are two important downstream signaling pathways regulated by Grb2 and then facilitate tumor progression." (PMID 30479571, 2018). "GRB2 has previously been shown to be involved in BCa progression, in vitro as well as in murine models in which its expression level was correlated with tumor growth." (PMID 28912526, 2017). "Consistent with the results of colony formation experiment, knockdown of endogenous Grb2 dramatically suppressed tumor growth, which was rescued by ectopic re-expression of Grb2WT but not Grb2K56R." (PMID 24775912, 2014). "Xenograft tumor model in mice was conducted to verify that Grb2 SUMOylation regulated tumorigenesis in vivo." (PMID 24775912, 2014). "More importantly, the combined GRB2 and GAB1 protein expression was significantly associated with aggressive tumor progression and poor prognosis in patients with HCC." (PMID 24391994, 2013). "GRB2-immune signaling interactome indicates crosstalk between calcium and cytokine signaling pathways in tumor cells to invoke cellular responses to fight and evade the host immune system in the process of neoplastic transformation." (PMID 23826330, 2013). "We observed a generic down regulation of phospho-proteome-GRB2 interaction network in the metastatic tumor cell MDA-MB-231 compared to MCF7 and T47D tumor cells." (PMID 23826330, 2013). "We found that SHP2pY584 shows very strong interaction with GRB2 in tumor cells (MCF7 and T47D) compared to MCF10A or MDAMB231." (PMID 23826330, 2013). "More importantly, the combined GRB2 and GAB1 protein expression was significantly associated with serum AFP (P=0.01), tumor stage (P=0.006) and tumor grade (P=0.02)." (PMID 24391994, 2013). "Consistent to the observation from SH2 domain binding phosphopeptide arrays, on a global scale, many GRB2-phosphoprotein interactions in MDA-MB231 are downregulated compared to tumor cells (MCF7 and T47D)." (PMID 23826330, 2013).
tumor (continued). "Three genes in this pathway had IRs >2 in our set of 47 primary tumors; EGFR in two tumors, ERBB2 in three tumors, and GRB2 in one tumor." (PMID 16457699, 2005). "Grb2-KD cells treated with Talazoparib also showed a significantly slower tumor growth rate." (PMID 38459011, 2024). "This suggests that in addition to its function of connecting RTK and cytoplasmic signaling pathways, GRB2 may also play a role in promoting tumor development in the nucleus." (PMID 38540680, 2024). "We recently confirmed phosphorylation of the PEAK3 TYSNL (pY24) motif in cells and showed this is required for recruitment of Grb2, and possibly CrkII and ASAP114, an Arf GTPase-activating protein that regulates cytoskeletal remodeling and is associated with tumor progression and invasiveness." (PMID 37336884, 2023). "This plays a tumour-suppressive role by competing with Grb2 to bind Sos." (PMID 36171279, 2022). "High expression of GRB2 in patients with KIRC may be related to tumor metastasis and could indicate a poor prognosis." (PMID 35127943, 2022). "This indicates that GRB2 is the gene that most varies among all the 6 tumor types analyzed." (PMID 35565454, 2022). "For instance, the direct interaction between ERRFI1 and GRB2 may preclude activation of the mitogen-activated protein kinase pathway and confer tumor suppressive effects." (PMID 32432675, 2020). "The experimental metastases model strengthens our hypothesis that GRB2 plays a late-stage tumour-promoting role both in vitro and in vivo." (PMID 30087284, 2018). "Furthermore, we demonstrate that restoration of the ECD cysteine residues is sufficient to rescue cell survival and tumor growth via a previously unreported pathway—BST-2/GRB2/ERK/BIM/Cas3." (PMID 28300825, 2017). "Additionally, inhibition of GRB2/pERK pathway limited tumor development by promoting cell apoptosis." (PMID 26885689, 2016). "Additionally, the GRB2 expression was highly reduced in the xenograft tumor tissue which exhibited high miR-329 expression." (PMID 26885689, 2016). "In addition, miR-329 mediated apoptotic response was significantly inhibited by the exogenous GRB2 expression which also resulted in dramatic inhibition of tumor growth in the xenograft model." (PMID 26885689, 2016). "Moreover, the combined GRB2 and GAB1 protein expression was significantly associated with aggressive tumor progression and poor prognosis in patients with HCC." (PMID 26204832, 2015). "As the results, we found that the expression levels of GRB2 protein in HCC tissues with the higher tumor stage (T3~4) and the positive serum AFP level were significantly lower than those with the lower tumor stage (T1~2, P=0.01) and the negative serum AFP level (P=0.006), respectively." (PMID 24391994, 2013). "Sos1(pY974) predicted to interact with GRB2 is an unreported novel interaction that we found upregulated in tumor cells might be a novel branch of Erk activation." (PMID 23826330, 2013). "Grb2 is significantly down-regulated in both tumor and stroma after both HBO treatments." (PMID 22251838, 2012). "However, based on bioinformatics analysis, we first supposed that DDX42 might be involved in the cell proliferation and treatment resistance phenotypes by urging the maturation process of GRB2, which has been fully understood in several tumour types." (PMID 40831000, 2025). "These phosphorylation events are essential for cellular invasion and distal tumor metastases formation through multiple mechanisms ultimately creating binding sites for scaffolding platforms composed by proteins such as Arp2/3, cofilin, N-WASp, Grb2, Nck1 and others." (PMID 34088320, 2021). "The positional candidate gene GAB3 is a member of the GRB2 binder family that includes scaffolding/docking proteins involved in signaling pathways mediated by growth factors, cytokines, and antigen receptors, and has roles in immune response and tumor cell proliferation." (PMID 31766405, 2019).
tumor (continued). "Although several signaling molecules, including Rac, Ras, Arf and Grb2, have been reported to regulate the formation of ruffling, proposed mechanisms for manipulating ruffling and the effect of these factors on cell migration and tumor metastasis are only beginning to emerge." (PMID 25537517, 2015). "Our tumor models were slightly different compared to the models published several years ago by other investigators, where the authors used the MMTV-Neu mouse model with Y1144 (YB) and Y1227 (YD) mutation in ErbB2 to activate specific HER2 signaling pathway - Shc or Grb2, respectively." (PMID 25280532, 2014). "Previous studies showed that E5 does not promote any changes in ERK activity in cultured fibroblasts as well as in BPV-induced tumours in vivo: it is therefore possible that pPDGFβR activates GRB2, Sos1, and Ras which may deviate on phosphatidylinositol-3-kinase/AKT pathway (PI3 K/AKT)." (PMID 23936786, 2013). "Interestingly, the coexpression of GRB2 and GAB1 may be associated with serum AFP, tumor stage, tumor grade and patient prognosis." (PMID 24391994, 2013). "GRB2, a key molecule in the RAF/MEK/ERK pathway, mediates tumor cell proliferation, invasion, and migration." (PMID 40883741, 2025). "Stabilized and upregulated GRB2 activates the Ras-MAPK pathway, thus promoting angiogenesis in the tumor microenvironment and advancing tumor development." (PMID 39845976, 2024). "After SUMOylation, GRB2 enhances ERK activity, promotes tumor development, and enhances cell migration ability." (PMID 38540680, 2024). "Consistently, the confusion matrix statistics showed that the normal and tumor samples can be reliably separated using gene expression data for CD2AP, GRB2, WASL, SRC, CTTN, CAPZA1, and Tks4 with 97% sensitivity and 80% specificity." (PMID 39234565, 2024). "Together, these results provide a platform for antigenic target identification using tumor-isolated B cells and protein arrays, and reveal CCDC155, PDP2 and GRB2 as the tumor-expressed target antigens recognized by Ab36, Ab73 and Ab89, respectively." (PMID 39086481, 2024). "The initial goal of the project was to determine the role of GRB2 in the inhibition of autophagy via the HER2 and BECN1 axis, as well as its implications in tumor growth." (PMID 38182563, 2024). "We found that the sensitivity of the WASL, GRB2, SRC, and Tks4 gene expression set was high for both tumor types (0.96 and 0.99), but the specificity values were low." (PMID 39234565, 2024). "Thus, GRB2 can regulate oncogene expression and may have consequences for tumour pathogenesis." (PMID 37328606, 2023). "For instance, it has been reported that nSH3/cSH3 binding peptides, which effectively interrupt the Grb2–SOS interaction, can serve as tumor suppressors." (PMID 35463958, 2022). "During tumor progression, CAPZA1, GRB2, NF2EL3, PLEKHO1, SIGLEC1, and UBE2Z were expressed at higher levels in late-stage KIRC, whereas EMX2, FUCA1, IMPA2, and RORC were expressed at higher levels in early-stage KIRC." (PMID 35127943, 2022). "The ERK required for cytoskeletal remodeling interacts with SHC or GRB2 to form an SHC-GRB2-ERK complex, which is a key component of TGF-β-induced tumor invasion and metastasis." (PMID 31195692, 2019). "These proteins included EGFR (a receptor of the EGFR pathway that we found activated in QM-PDAC tumours), SOS1 and GRB2 (both of which are upstream signalling proteins in the canonical MAPK signalling pathway)." (PMID 30018740, 2018). "Consistent with the in vitro results, overexpression of miR-133b significantly restrained the tumor growth and lung metastases via regulating EGFR/ITGB4/FAK/Grb2 signaling pathway." (PMID 30479571, 2018). "In regards to kinase signaling, up-regulation on the protein level in the tumor was detected on both upstream and downstream of the mTOR including AKT1, PI3Kα, GRB2, mTOR, DPTOR, S6K and S6, which is known to be highly mutated in cancer." (PMID 29109428, 2017).
tumor (continued). "FAK signaling has been shown to regulate proteins (e.g. SRC, SYK, FYN, LYN, GRB2, PI3K, and paxillin) that are involved in modulating cytoskeleton rearrangements to enhance tumor growth and metastasis." (PMID 27472394, 2016). "In a human intrahepatic CC cell line, downregulation of miR-376c, which is suggested to function as a tumor suppressor, accelerated EGF-dependent migration through its direct target growth factor receptor bound protein 2 (GRB2)." (PMID 26729094, 2015). "The results show elevated Grb2 expression and phosphorylation, MAP kinase and tyrosine kinase activity in the tumour samples compared with the normal cohort." (PMID 26103942, 2015). "Concerning the genes related to tumor progression, we found HSP90AB1, GRB2, ERBB2/3, EIF4A3, HDGF, and CSNK2B." (PMID 25625699, 2015). "GRB2 positive staining was localized in the cell nucleus and cytoplasm, while GAB1 positive staining was localized in the cytoplasm of tumor cells in HCC tissues." (PMID 24391994, 2013). "GRB2 interaction with SHC1 (pY439 and pY427) has been shown in T cells to induce Ras-Erk signaling and CD69 leading to tumor cell survival and promoting tumor vascularization." (PMID 23826330, 2013). "At present, there were no reports about the association between GRB2 and DDX42 regarding regulating tumour progression and treatment resistance." (PMID 40831000, 2025). "Additionally, we demonstrated that the expression differences between tumour and normal tissues of DDX42 and GRB2 in HCC specimens via IHC experiments." (PMID 40831000, 2025). "In conclusion, our findings facilitate the acknowledgment of tumour initiation and mechanisms of treatment resistance in HCC, and targeting the axis of DDX42 and GRB2 may be promising strategies for synergy with radiotherapy or sorafenib for HCC patients." (PMID 40831000, 2025). "Grb2 SUMOylation recruits Sos1 (son of sevenless homolog 1) for the formation of Grb2-Sos1 results in the initiation of signaling pathway RAS/MEK/MAPK that consequently plays pivotal roles in carcinogenesis, cell migration, and tumor development." (PMID 38590645, 2024). "In the case of the TCGA COAD dataset, the combined ROC curve of WASL, GRB2, SRC, and Tks4 gene expression yielded the same high accuracy as before (AUC value = 0.98), indicating that the separation of normal and tumor samples is achievable based on the reduced gene set’s expression data." (PMID 39234565, 2024). "Specifically, by targeting TNK1, an inhibitor of the Grb2-Sos1 GEF complex, miR-135b-5p may activate the MAPK/ERK signaling pathway and in turn promote tumor progression." (PMID 36755690, 2023). "While genetic amplification of GRB2 is not a feature of tumour cells, enhanced GRB2 expression has been recorded in various cancers." (PMID 37328606, 2023). "This hypothetical functional complex consisting of BAG3, HYOU1, GRB2, UBAP2L and DNAJB4 could be very important in PDAC since, in addition to BAG3, interactors also play an important role in tumor pathology." (PMID 35406724, 2022). "Targeting the LINC01234/miR-124-3p/GRB2 axis reportedly increased the expression of miR-124-3p and inhibited the expression of the GRB2 protein through the downregulation of LINC01234, which ultimately decreased the proliferation of the MM tumor cells." (PMID 36466549, 2022). "After validating the tumor-restraining effects of miR-27b-3p, and its negative correlation with Grb2 expression, we further assessed their functional relationship in GC cells." (PMID 34162761, 2021). "Regarding tumor grade, the higher expression of VEGF-B (log FC = 10.8, p = 0.002), GRB2 (log FC = 2.4, p = 0.01) and RAC1 (log FC = 1.8, p = 0.02) genes were detected in mammary carcinoma tumor tissue, compared to adjacent tissue in group of all breed dogs with tumor grade III (n = 13)." (PMID 34679042, 2021).
tumor (continued). "According to our experiment and previous studies, we speculate that GL-pp might inhibit tumor metastasis by disturbing the function of FAK and the pathway involving Ptk2 and Grb2." (PMID 34305583, 2021). "The functional GRB2 protein acts as a negative regulator of the RAS pathway by inhibiting EGFRs, and SMYD4 is involved in inhibition of gene expression and has been suggested as a tumor suppressor gene." (PMID 32885540, 2020). "Worth to note, CNAs of 37 genes were exclusively found in G3 tumours such as WNT7B (4 gains), BAD (3 gains), WEGFB (3 gains) and HDAC2 (3 losses) in respect to 65 CNA genes exclusively presented in G1 tumours, such as GRB2 (5 losses) and FGF21, STAT3, CTNNA3 and DVL3 with 3 losses each." (PMID 28486536, 2017). "Thus, we conclude that both routes to PI3K activation, emanating from ErbB2/Grb2/RAS and ErbB3, must be interrupted to achieve full anti-tumour response." (PMID 27255951, 2016). "Further experimental validation indicated that the aberrant expression of GRB2 and GAB1 proteins may be strongly related to tumor progression and prognosis in patients with HCC." (PMID 24391994, 2013). "Notably, components of the EGF signaling network, Adam10, a metallopeptidase that processes EGF, and Grb2, an adaptor protein that binds directly to the EGF receptor, exhibited a greater importance for transgenic than for tumor TFs (blue dots)." (PMID 21464922, 2011). "Another recent study uncovered that exosomal GP73 from tumor cells can enter vascular endothelial cells, competitively binding to the E3 ubiquitin ligase HECT domain containing 1 (HECTD1), preventing the ubiquitination of substrate protein growth factor receptor-bound protein 2 (GRB2)." (PMID 39845976, 2024). "In addition, past studies have also revealed the interactions between GRB2 different domains and non-receptor tyrosine kinases and other signaling molecules, which also contribute to tumor growth, invasion, and metastasis." (PMID 38540680, 2024). "In addition, two factors of RAS signaling pathways, GRB2 and DUSP6, may be involved in the invasiveness of circulating tumor cells through intricate interactions with the suppressor gene EXT2." (PMID 36672653, 2023). "Inhibition of the Grb2 expression in mice via liposomal antisense oligodeoxynucleotide DOPC liposomes has shown decreased tumor growth (0.29 g ± 0.14 g, p < 0.05) and a greater decrease in tumor weight when treated in combination with Paclitaxel (0.82 g ± 0.25 g, p < 0.05)." (PMID 37612696, 2023). "In addition, we found that the expression levels of T-cell exhaustion-related genes including CD40, GRB2, MKI67, NFATC3, PRDM1, TCF7, and TGFB1 were significantly higher, while those of CXCR5 and TOX were significantly lower after tumor recurrence (all p < 0.05)." (PMID 34305618, 2021). "Interestingly, targeting CBL E3 ligases may also have synergistic effects in certain tumor cell types, such as melanoma, where c-CBL has recently been shown to promote tumor growth and mobility in part via the focal adhesion kinase (FAK)-GRB2-SRC nexus." (PMID 29794999, 2018). "In line with our recent results that miR‐634 functions as tumor suppressor by targeting CYR61 through Raf‐ERK signaling, van Jaarsveld MT also found that the cell cycle regulator CCND1 and Ras‐MAPK pathway components GRB2, ERK2, and RSK2 were directly repressed by miR‐634 overexpression." (PMID 29473317, 2018). "Similar to Grb10, Grb2, Grb7 and Grb14 expression varied among different control organs examined, however none were overexpressed in any tumor cell line compared to control tissues, arguing against compensatory overexpression of Grb family members in response to reduced Grb10 expression." (PMID 26000738, 2015). "Notably, hypoxic tumor cells with constitutive and high EGFR activation (CAL-27 and HN30 cells) appear to employ some previously unknown antagonistic mechanisms to bypass the inhibitory effect of ubiquitination-mediated degradation by blocking the binding of Cbl/Grb2 to EGFR." (PMID 40940319, 2025).